PTENP1 (phosphatase and tensin homolog pseudogene 1)
Diseases named in the same sentence as PTENP1 in open-access papers (continued):
Sharing a sentence is not in itself a finding about the gene and the disease.
glioma (9 papers, 2012 to 2025). A benign or malignant brain and spinal cord tumor that arises from glial cells (astrocytes, oligodendrocytes, ependymal cells). "PTENP1 is found to be downregulated in glioma tissues, causing inhibition of both proliferation and invasion of glioma cells." (PMID 31681595, 2019). "PTENP1 is reduced in cancer tissues compared to normal tissues, and lower PTENP1 levels predict worse overall survival, raising the possibility of PTENP1 as a novel diagnostic biomarker and treatment for glioma." (PMID 40647484, 2025). "Two hundred and seventy-nine glioma patients were recruited and grouped according to their genotypes of rs7853346 in PTENP1 and rs1799864 in CCR1." (PMID 37047356, 2023). "On the other hand, in acute myeloid leukemia and lower grade glioma patients PTENP1 hypermethylation strongly correlated with favorable prognosis." (PMID 33481830, 2021). "One study reported that exosomal lncRNA PTENP1, secreted by human umbilical cord MSCs, could be transferred into human glioma U87 cells and inhibit the cancerous progression of glioma cells through the PTENP1/miR-10a-5p/PTEN pathway." (PMID 40647484, 2025). "They found that lncRNA PTENP1 could be packaged into hucMSC-Exo and transferred to glioma cell line U87 cells, where it bound to miR-10a-5p in tumor tissues." (PMID 38994350, 2024). "Indeed, according to our data analysis, in lower grade glioma, acute myeloid leukemia and endometrial cancer patients with higher methylated PTENP1 show prolonged survival." (PMID 33481830, 2021). "Although PTENP1 is also found to be involved in regulating the proliferation and invasion of glioma cells, whether its anti-tumor effect is mediated by ceRNA mechanism has not been reported." (PMID 33995499, 2021). "Furthermore, exosomes, including lncRNA PTENP1, secreted by human umbilical cord mesenchymal stem cells inhibited glioma cell growth, which indicates that exosomes might be useful for introducing lncRNAs in glioma." (PMID 34202078, 2021).
endometrial cancer (8 papers, 2017 to 2025). Primary or metastatic malignant neoplasm involving the endometrium (mucous membrane that lines the endometrial cavity). "The methylation status of the PTEN tumor suppressor gene and PTENP1 pseudogene in endometrial cancer was assessed by the COBRA method." (PMID 38982390, 2024). "Another study showed that PTEN (tumor suppressor) and PTENP1 (PTEN homologous) are two direct targets of miR-200 in endometrial cancer cells." (PMID 34122542, 2021). "For endometrial carcinoma we found some correlation between higher PTENP1 methylation and more favorable prognosis for patients, however the differences were not quite statistically significant (p = 0.071)." (PMID 33481830, 2021). "In endometrial cancer, patients with PTENP1-positive tumours exhibited a trend towards lower disease recurrence." (PMID 28112249, 2017). "Therefore, estrogen also regulates miR-200-PTEN/PTENP1 by binding ERα and then modulates endometrial cancer viability and aggressiveness." (PMID 34122542, 2021). "In order to test this hypothesis, we investigated the relationship between the level of PTENP1 expression and the overall survival of patients with endometrial carcinoma." (PMID 33481830, 2021). "Therefore, we decided to divide the patients into age groups and compare the frequencies of PTENP1 methylation in normal endometrium, endometrial polyps, endometrial hyperplasia and endometrial carcinoma within each of the age groups, as well as compare the age groups with each other." (PMID 33481830, 2021). "In endometrial cancer, estrogen binds to ER, increasing miR-200c levels and inhibiting PTEN and PTENP1, which activates the PI3K-AKT pathway." (PMID 40243588, 2025). "Therefore, both PTENP1 and miR-200c are involved in decreasing PTEN levels and tumor growth in breast and endometrial cancer." (PMID 40877546, 2025). "For example, miR-200c promotes the development of endometrial cancer by increasing estrogen levels,which play a crucial role in the progression of cancer because of its effects on both PTEN and PTENP1, as PTEN levels have been reported to decrease in endometrial cancer as a result of estrogen." (PMID 40877546, 2025). "In our previous study we demonstrated the absence of a correlation of PTENP1 methylation with the clinical characteristics of endometrial cancer (disease stage, FIGO grade, myometrium invasion)." (PMID 33481830, 2021).
head and neck squamous cell carcinoma (8 papers, 2017 to 2023). A squamous cell carcinoma that arises from any of the following anatomic sites: lip and oral cavity, nasal cavity, paranasal sinuses, pharynx, larynx, and salivary glands. "Upregulation of PTENP1 led to inhibited proliferation, colony formation and migration in vitro and suppressed growth in vivo in head and neck squamous cell carcinoma." (PMID 32185172, 2020). "PTENP1 was downregulated in head and neck squamous cell carcinoma and its low expression correlated with poor patients’ prognosis." (PMID 32185172, 2020). "For instance, low expression of PTENP1 was related with decreased cell invasion and poor prognosis in several cancer types including melanoma and head and neck squamous cell carcinomas." (PMID 29078818, 2017). "In head and neck squamous cell carcinoma cell lines, complete and partial losses of PTENP1 are known to be frequent; however, the deletion of genomic PTEN is not common, further providing evidence for PTENP1 being under selective pressure to undergo copy number loss in cancer." (PMID 37894321, 2023). "However, overexpression of PTENP1 did not successfully restore PTEN to normal levels in head and neck squamous cell carcinoma cell lines, HN13 and HN30." (PMID 37894321, 2023). "Furthermore, high expression of PTENP1 (a pseudogene of PTEN) might result in better OS and DFS rates of head and neck squamous cell carcinoma (HNSCC) patients." (PMID 30881525, 2019).
melanoma (8 papers, 2017 to 2021). A malignant, usually aggressive tumor composed of atypical, neoplastic melanocytes. "Since the loss of the PTENP1 locus is accompanied by reduced PTEN expression in melanoma and colon cancer, PTENP1 has been shown to regulate PTEN post-transcriptionally and act as a decoy for PTEN-targeting mRNA." (PMID 35011635, 2021). "For example, deletion of the PTENP1 pseudogene locus in melanoma enhances miRNA-mediated suppression of PTEN and tumor progression." (PMID 33466728, 2021). "In parallel, we observed decreased expression of PTENP1 in primary melanoma compared with nevus." (PMID 35096622, 2021). "Several studies have identified known lncRNAs that are abnormally expressed in melanoma, such as SAMMSON, HOTAIR, SLNCR1, BANCR, SPRY4-IT1, ANRIL, Llme23, UCA1, MALATA1, GAS5, H19, CASC15, PTENP1, and MIR31HG." (PMID 28225791, 2017). "LncRNA PTENP1 was a crucial negative mediator of PTEN and was frequently deleted in 14-21% of melanoma." (PMID 35096622, 2021).
colon cancer (7 papers, 2012 to 2024). "Further there was a direct relationship between PTENP1 copy number and PTEN expression in colon cancer tissues, indicating that PTENP1 transcript levels can regulate PTEN expression and thus act as a tumor suppressor." (PMID 24523727, 2014). "The direct association between PTENP1 and PTEN expression in tumor specimens from colon cancer patients suggests that PTENP1 transcript may act as a tumor suppressor by regulating PTEN expression." (PMID 39403602, 2024). "Furthermore, decreasing of the copy number of PTENp1 was observed insporadic colon cancer, which was correlated with a decrease of PTEN, thus leading to the proposal that PTENp1 is a bona fide tumour suppressor gene." (PMID 27936183, 2016).
cervical cancer (6 papers, 2021 to 2025). A primary or metastatic malignant neoplasm involving the cervix. "In cervical cancer, PTENP1 targets key regulatory pathways by enhancing the expression of the tumor suppressor PTEN through the sequestration of miR-106b, inhibiting cell growth, motility, and EMT, crucial factors in cancer progression and metastasis." (PMID 40242248, 2025). "As a result, PTENP1 suppress cell growth, motility and epithelial-to-mesenchymal transition and inhibits cervical cancer progression." (PMID 33481830, 2021). "Similarly, PTENP1 could inhibit progression of cervical cancer through different mechanisms including suppression of miR-106b, miR-27a-3p and miR-19b." (PMID 35655204, 2022). "Another lncRNA, TUSC8, demonstrated tumour-suppressive roles in cervical cancer where it focuses on the inhibition of invasion and migration through the miR-641/PTEN axis, similar to PTENP1, but with a specific miRNA target." (PMID 40242248, 2025). "Another top-ranked feature, MTUS1, acts via the PTENP1/miR-19b/MTUS1 axis to suppress proliferation and invasion in cervical cancer and is often downregulated in aggressive tumors." (PMID 40951335, 2025). "In cervical cancer, lncRNA FAM13A-AS1/miRNA-205-3p/DDI2 axis and lncRNA PTENP1/miR-106b/PTEN axis can jointly promote apoptosis and inhibit the progression of cervical cancer, while lncRNA HOXD-AS1 plays an anti-apoptosis role to promote the progression of cervical cancer." (PMID 37313458, 2023).
oral squamous cell carcinoma (6 papers, 2017 to 2024). "PTENP1 acted as a competing endogenous RNA to protect PTEN transcripts from being inhibited by miR-21, and consequently inhibited proliferation and colony formation in oral squamous cell carcinoma (OSCC)." (PMID 31196157, 2019).
esophageal squamous cell carcinoma (3 papers, 2019 to 2025). Esophageal squamous cell carcinoma (ESCC) is a type of esophageal carcinoma (EC) that can affect any part of the esophagus, but is usually located in the upper or middle third. "They found a downregulated expression of PTENP1 in esophageal squamous cell carcinoma compared with the corresponding adjacent normal tissues and overexpression of PTENP1 inhibited tumor proliferation (esophageal squamous cell carcinoma)." (PMID 32185172, 2020). "In esophageal squamous cell carcinoma (ESCC), overexpression of PTENP1 resulted in inhibited proliferation." (PMID 31196157, 2019). "However, greater complexity was observed, as PTENP1 overexpression in esophageal squamous cell carcinoma cells increased PTEN levels in Eca19 cells but not in TE-1 cells." (PMID 40877546, 2025).
glioblastoma (3 papers, 2022 to 2025). The most malignant astrocytic tumor (WHO grade IV). "These vesicles (which carry PTENP1) are also delivered to glioblastoma cells (U87MG), where they act as sponges for miR-10a-5p, stabilize PTEN levels, and prevent its competitive suppression." (PMID 40877546, 2025). "This relationship can be exploited in treating certain cancers, such as glioblastoma cells, by making PTENP1 a target for PTEN." (PMID 40877546, 2025). "PTENP1 packaged into exosomes has also been transferred to U87MG glioblastoma cells to sponge miR-10a-5p and stabilise PTEN levels in a competitive manner." (PMID 37894321, 2023). "Thus, in glioblastoma cells, PTENP1 is a downstream target of PTEN." (PMID 37894321, 2023). "While regulation of PTEN by PTENP1 is well established, a recent report has shown regulation of PTENP1 by PTEN in glioblastoma cells." (PMID 37894321, 2023).
renal cell carcinoma (3 papers, 2017 to 2020). "For example, PTENP1 is a pseudogene of the tumor suppressor gene PTEN that is downregulated via methylation in renal cell carcinoma with PTENP1 a competing non-endogenous RNA to suppress cancer progression." (PMID 30161129, 2018).
endometrioid endometrial carcinoma (2 papers, 2018 to 2023). "Additionally, the low PTENP1 expression in endometrioid endometrial carcinoma and leukemia cells was shown to be associated with genomic copy number loss of PTENP1." (PMID 37894321, 2023). "A study in endometrioid endometrial carcinoma cells showed that an increase in miR-200c increased estrogen, resulting in a decrease in PTEN and PTENP1 expression in cells." (PMID 37894321, 2023).
liver cancer (2 papers, 2021 to 2026). An epithelial or non-epithelial malignant neoplasm that arises from the liver. "UFC1 expression was increased progressively with advancing fibrosis grade and Barcelona Clinic Liver Cancer (BCLC) stage, while PTENP1 levels diminished with BCLC stage." (PMID 42042020, 2026).
lung carcinoma (2 papers, 2018 to 2022). "We found the top 30 lncRNAs associated with lung cancers and inferred that lncRNAs TUG1, PTENP1, and UCA1 may be biomarkers of lung neoplasms, non-small–cell lung cancer, and LUAD, respectively." (PMID 35938010, 2022).
endometrial polyp (1 paper, 2021). A benign nodular lesion protruding above the surface of the endometrium. "Our data allow us to conclude that PTENP1 methylation reflects age-related changes that occur in normal and hyperplastic endometrium (but not in endometrial polyps)." (PMID 33481830, 2021).
endometrioid carcinoma (1 paper, 2023). "Similarly, another study in endometrioid carcinoma cells showed that an increase in miR-200c increased estrogen, resulting in an observed decrease in PTEN and PTENP1 expression in cells." (PMID 37894321, 2023). "Estrogen plays an essential role in the occurrence of endometrioid carcinoma and affects the negative feedback loop of PTEN-miR-200c-PTENP1." (PMID 37894321, 2023). "Therefore, estrogen plays an essential role in the occurrence of endometrioid carcinoma and affects the negative feedback loop of PTEN-miR-200c-PTENP1." (PMID 37894321, 2023).
endometriosis (1 paper, 2022). The growth of functional endometrial tissue in anatomic sites outside the uterine body. "In this study, we investigated the possible impacts of genetic variations in these ovary-related lncRNAs, PTENP1, GAS5 and UCA1, on endometriosis." (PMID 35901079, 2022). "Since endometriosis shares several features with cancer, we investigated the possible involvement of cancer-related lncRNAs in endometriosis, including UCA1, GAS5 and PTENP1." (PMID 35901079, 2022).
Insulin resistance (1 paper, 2022). Increased resistance towards insulin, that is, diminished effectiveness of insulin in reducing blood glucose levels. "Animal models have also been used to evaluate the impact of PTENP1 in insulin resistance." (PMID 35655204, 2022).
liver diseases (1 paper, 2020). "The levels of serum HULC, MALAT1, Linc00152, PTTG3P, SPRY4-IT1, UBE2CP3, and UCA1 were significantly higher in HCC patients than in patients with benign liver diseases and healthy controls, whereas serum PTENP1 was significantly decreased in HCC patients compared with healthy participants." (PMID 32733618, 2020).
Lung Diseases (1 paper, 2019). "The top predicted genes were DAB2 and PTENP1 and the top ranked diseases were Lung Diseases and Ovary Syndrome." (PMID 31345171, 2019).
lung neoplasm (1 paper, 2022). A benign or malignant, primary or metastatic neoplasm involving the lungs. "We predict that TUG1, PTENP1, and UCA1 may be the biomarkers of lung neoplasms, NSCLC and LUAD, respectively." (PMID 35938010, 2022).
oral cancer (1 paper, 2018). "Moreover, in oral cancer cells PTENP1 down-regulates the expression of miR-21 and influences PTEN expression." (PMID 30441874, 2018).
sarcoma (1 paper, 2021). A usually aggressive malignant neoplasm of the soft tissue or bone. "In contrast, in sarcoma, PTENP1 methylation is correlated with a poor prognosis." (PMID 33481830, 2021).
tumor (85 papers, 2011 to 2026). "The growth of human LSCC xenograft was remarkably inhibited by HOTAIR shRNA lentivirus treatment, and injection of the PTENP1-expressing baculovirus effectively mitigated the HCC xenograft tumor growth, which was associated with the increase of PTEN." (PMID 30217221, 2018). "Thus, like PTEN, PTENP1 also functions as a tumor suppressor, and PTENP1 upregulation causes growth inhibition of tumor cells." (PMID 30071685, 2018). "Among cancer‐associated pseudogenes, PTENP1 represents a paradigm‐shifting discovery that fundamentally altered our understanding of pseudogene biology, serving as the representative well‐characterized example of a tumor‐suppressive pseudogene functioning through microRNA decoy mechanisms." (PMID 41473691, 2025). "The pervasive dysregulation of pseudogenes across cancer types—with some functioning as tumor suppressors (e.g., PTENP1) and others as oncogenic drivers (e.g., KRASP1, BRAFP1)—highlights their importance as a novel class of cancer genes." (PMID 41473691, 2025). "By upregulating PTEN, TUSC8 curtails pathways essential for cancer cell invasiveness, supporting a role that complements both MEG3 and PTENP1 in modulating the tumor microenvironment." (PMID 40242248, 2025). "The reduced expression of Ki-67 (as in our clinical results) was also noted; thus, all the results demonstrated the tumor suppressive role of PTENP1 in BC cells." (PMID 38277283, 2024). "PTENP1, a long non-coding RNA, has been shown to suppress tumor growth through the rescuing of PTEN expression via a competitive endogenous RNA (ceRNA) mechanism." (PMID 38965509, 2024). "This further validates the use of PTENP1 expression levels as a potential future candidate prognostic biomarker due to its tumour suppressor activity." (PMID 37894321, 2023). "The injection of the PTENP1 expressing baculoviral vector into mice with HCC tumours also reduced tumour growth and cell proliferation, induced apoptosis and autophagy, and inhibited HCC cell properties." (PMID 37894321, 2023). "The results of conducted experiments have indicated that up-regulation of PTENP1 can decrease tumor weight and burden." (PMID 35655204, 2022). "PTEN pseudogene (PTENP1) is one of the ceRNAs correlated with PCa, which is linked to PTEN phosphatase as a tumor-suppressive pseudogene." (PMID 36514044, 2022). "The sense transcript of PTENP1 pseudogene exhibits the properties of tumor suppressive lncRNA in many types of human cancer." (PMID 33481830, 2021). "In our previous study we showed that PTENP1 methylation is present not only in tumor, but also in normal endometrium tissues of women over 45 years old." (PMID 33481830, 2021). "This type of lncRNA can act as an miRNA sponge, binding to miRNAs thanks to their complementary sequence; PTENP1 (phosphatase and tensin homolog pseudogene 1), for example, leads to tumor suppressor activity due to the decoy of different miRNAs." (PMID 33923983, 2021). "In clear-cell renal cell carcinoma overexpression of PTENP1 in cells reduced cell proliferation, migration, and invasion in vitro and tumor growth and metastasis in xenograft models." (PMID 32314732, 2020). "PTENP1 is a tumor suppressive pseudogene-derived lncRNA reported in multiple types of cancer as well as brain glioma." (PMID 32185172, 2020). "Exosomal lncRNA PTENP1 inhibits tumor progression by regulating PTEN expression via binding to microRNA-17." (PMID 33281872, 2020). "In esophageal squamous cell carcinoma and oral squamous cell carcinoma, overexpression of PTENP1 decreased proliferation and colony formation in vitro and inhibited tumor growth in xenograft models." (PMID 32314732, 2020). "On the other hand, NEAT1 and PTENP1, commonly known as tumor suppressors in various cancer types, have been shown to potentiate cell growth and tumor progression in breast cancer." (PMID 32392629, 2020). "The expression of PTEN, the parental gene of PTENP1, in the same paired biopsies was reduced in tumor tissues." (PMID 31196157, 2019).